CCL3 (C-C motif chemokine ligand 3)
Diseases named in the same sentence as CCL3 in open-access papers (continued):
Sharing a sentence is not in itself a finding about the gene and the disease.
breast carcinoma (57 papers, 2015 to 2025). "Other research has shown that Ccl3 and Ccr1 expressed by tumor-associated Macrophages is associated with enhanced interaction with breast carcinoma cells and metastatic seeding to the lung." (PMID 39026350, 2024). "In this study, a “chemokine cascade” was discovered in which breast carcinoma cells activate CCR2 on metastasis associated macrophages which controls the expression of CCL3." (PMID 36982211, 2023). "On the other hand, CCL3 has been implicated in promoting breast cancer metastasis to the lungs." (PMID 27169366, 2016). "Proteins involved in chemotaxis and inflammation, including CCL3, CCL4, CXCL11, and CCL23, were only found to be associated with long-term breast cancer risk after five years, suggesting the long-term effect of inflammation on breast cancer risk." (PMID 40665092, 2025). "In mammary tumors, Ccl2, Ccl3 and Ccl5 were shown to modulate the infiltration of monocytes, resulting in the accumulation and activation of tumor-associated macrophages, TAMs." (PMID 39566333, 2025). "Genetic deletion of CCL3 or CCR1 prevented pulmonary metastasis in the PyMT breast cancer murine model and thus it was concluded that the CCL3/CCR1 axis activated in macrophages is responsible for metastatic seeding of the lung." (PMID 36982211, 2023). "CCL2/CCR2 signalling has been shown to promote the activation of the CCL3 (MIP-1α)/CCR1 signalling cascade in breast cancer metastasis to the lung, leading to the retention of metastasis associated macrophages and colony growth." (PMID 36241867, 2022). "For example, Sox2+ breast cancer cells attracted macrophages to the TME by secreting (C-C motif) chemokine ligand 3 (CCL3) and intercellular adhesion molecule 1 (ICAM-1) chemokines." (PMID 36613838, 2022). "Our findings provide possibilities to extend PARP inhibitors for the treatment of BRCA-WT breast cancer patients or PARP inhibitor-resistant patients through cotreatment of CCL3, β-catenin inhibitors, anti-RANKL antibody, or bisphosphonates." (PMID 32221289, 2020). "We tested the effect of rescuing CCL3 level in the bone metastatic microenvironment by CCL3 overexpression in breast cancer cells." (PMID 32221289, 2020). "CCL2-CCR2 axis has been reported to enhance TAMs secretion of CCL3 at the pre-metastatic sites, thus sustaining lung metastasis seeding in mouse models of breast cancer." (PMID 30591657, 2018). "Results from our breast cancer metastasis model suggest that the inhibition of CCL3 secretion from MAMs is one of the possible strategies as they are a major source of CCL3 among other leukocytes such as neutrophils, T, B, and NK cells in the metastatic lung." (PMID 26275794, 2015). "CCL2 is another possible target fitting this strategy since CCL2 neutralizing antibody can suppress Ccl3 expression in MAMs as well as their recruitment following mammary tumor metastasis." (PMID 26275794, 2015). "Moreover, CCL3 plays a vital role in promoting EMT via the PI3K-protein kinase B (Akt)-mTOR signaling pathway in breast cancer cells when co-cultured with myeloid-derived suppressor cells." (PMID 39684816, 2024). "Further, inhibition of CCL3-CCR1 (CC-chemokine receptor-1) axis using anti-CCL3 antibody or deletion of CCL3/CCR1 could effectively reduce breast cancer lung metastasis." (PMID 38037106, 2023). "For example, the CCL3/CCR1 axis was found to mediate macrophage recruitment during the formation of early metastatic niches in a mouse E0771-LG breast cancer model, and CCL3/CCR5 mediated macrophage recruitment to the metastatic site in murine Renca renal cell carcinoma model." (PMID 34988021, 2021). "CCL3 secreted by breast cancer cells recruits MDSCs, which activates the PI3K-AKT-mTOR pathway in breast cancer cells, thereby inducing the epithelial-mesenchymal transition (EMT) and tumor cell migration and invasion in co-cultures of human breast cancer cell lines and MDSCs." (PMID 32726950, 2020).
breast carcinoma (continued). "Our data implies loss of CCL3 and CCL8 in breast cancer could lead to enhanced cell proliferation and tumor progression." (PMID 31620367, 2019). "Our data implies loss of CCL3 and CCL8 in breast cancer could lead to enhanced cell proliferation and progression." (PMID 31620367, 2019). "Interestingly, a recent report suggests that CCL3 released from E0771 breast cancer cells increases expression of CCL7, CCL8, CCL11, and CCL12 in the lung." (PMID 30483271, 2018). "As T cell migration is orchestrated by responses to chemokine gradients, we first compared the relative mRNA expression of a panel of chemokines to which naive T cells respond — CCL3, 4, 18, 19 and 21 — in 52 breast cancers vs paired adjacent normal breast tissues." (PMID 28290464, 2017). "Interestingly, CCL-3, which was unaltered in both breast cancer and dense breast tissue, has been shown to be important for breast cancer progression and metastases in experimental animal models." (PMID 29387062, 2017). "Because we previously reported that CXCL5, CCL2, CCL3, and CCL5 occur at low levels in CM collected from aggressive breast cancer cell lines, here we focused on other abundantly secreted chemokines." (PMID 40833805, 2025). "In both the mammary carcinoma and fibrosarcoma cells, secretion of CCL2, CCL3, CCL4, and Cxcl10 was upregulated after poly(I:C) transfection." (PMID 35737804, 2022). "We observed significant positive correlations across 23 different tumor types, including breast cancer, between CD8+ T-cell infiltration and all probed chemokines and cytokine genes, with Ccl3 being the least correlated." (PMID 34446712, 2021). "In the E0771-LG metastatic breast cancer model, a CCR1 ligand, CCL3, is expressed by MAMs at higher level than other types of tumor-infiltrating immune cells or circulating monocytes, and loss of Ccl3 reduces MAM accumulation in the metastatic lung." (PMID 30483271, 2018). "In addition, blockade of the CCL3/CCL4 receptor CCR5 has been shown to suppress tumor growth and myeloid cell infiltration in a murine model of breast cancer." (PMID 38108458, 2024). "The aggregation of 27-HC stimulates the proliferation of estrogen receptor-positive breast cancer cells, promotes the expression of various chemokines such as CCL2 and CCL3 by TAMs and recruits monocytes to the primary tumor site, which in turn promotes the development of breast cancer." (PMID 37004014, 2023). "Breast cancer cell-derived supernatant treated neutrophils significantly expressed high levels of interleukin-1β (IL-1β), CC-chemokine ligand-2-4 (CCL2, CCL3, CCL4), inducible nitric oxide synthase (iNOS), and matrix metallopeptidase-9 (MMP9), and formed extracellular traps (NETs)." (PMID 33049964, 2020). "CCL3 via CCR1 signaling promote metastasis in lung and breast cancer." (PMID 33062602, 2020). "CCR4, whose ligands are CCL2, CCL3, CCL5, CCL17 and CCL22, is crucial for immune cell homeostasis but is also involved in hematologic malignancies, such as adult T-cell leukemia and Hodgkin’s lymphomas, and some solid tumors, including breast cancer." (PMID 30591657, 2018). "Our data showed overexpression of proinflammatory factors including CXCL1, CXCL2, CXCR4, CCL3, CCL4, IL-8, and PTGS2/COX-2 in the peripheral blood of patients with breast cancer both when considering the subtypes individually and when considering all breast cancer samples as a group." (PMID 26884644, 2016). "Intriguingly, CathD has also been shown to selectively degrade macrophage inflammatory protein (MIP)-1α (CCL3), MIP-1β (CCL4), and SLC (CCL21) that, in turn, may affect the generation of the anti-tumoral immune response, the migration of human breast cancer cells, or both processes." (PMID 26610586, 2015).
breast carcinoma (continued). "Additionally, many markers we observed that defined our monocyte clusters (FABP5, FN1, IL1RN, CCL3, CCL4, CXCL8, CXCL3, IL1B) during transient, short-term CM stimulation, were elevated in either PD-L1pos or PD-L1neg TAMs isolated and sequenced from breast cancer." (PMID 40176808, 2025).
melanoma (57 papers, 2007 to 2026). A malignant, usually aggressive tumor composed of atypical, neoplastic melanocytes. "The membranes exhibit clear upregulation of several chemokines in the melanoma SPNs, including CCL3, members of the GRO family (CXCL1/2/3), and IL-8, all of which are highlighted in red boxes." (PMID 40869222, 2025). "In mouse melanoma tumors, non-coding control plasmid DNA electrotransfer induces the secretion of CCL3 after 4 and 24 h and CCL4 after 4 h." (PMID 36297532, 2022). "Combining adenoviral delivery of CCL3 with the adoptive transfer of activated effector T cells significantly attracted activated T cells to the murine melanoma tumors." (PMID 33381115, 2020). "This plasmablast-like phenotype can be reconciled in human melanomas where plasmablast-like cells also express T cell-recruiting chemokines CCL3, CCL4, CCL5." (PMID 31519915, 2019). "For example, in melanoma, the upregulation of chemokine genes, such as Ccl2, Ccl3, Ccl4, Ccl5, Cxcl9, and Cxcl10, in the tumor microenvironment correlates with the influx of activated T cells into the tumor supporting the antitumor immune response." (PMID 29410666, 2018). "It has been shown that high levels of chemokines CCL3, CCL4, and CXCL8 in pre-treatment tumor specimens were associated with worse patient overall survival after anti-CTLA4 and Carboplatin/paclitaxel treatment in melanoma." (PMID 30873179, 2019). "In melanoma, it has been demonstrated that up regulation of expression of several chemokine genes such as Ccl2, Ccl3, Ccl4, Ccl5, Cxcl9, and Cxcl10 in the tumor microenvironment correlates with the recruitment of activated effector T cells to the tumor increasing antitumor immunity." (PMID 27876058, 2016). "Moreover, macrophages are a major source of CCL2, CCL3, CCL4, CCL5, CXCL9 and CXCL10, which are important chemokines that induce T lymphocyte chemotaxis, and which we find in association with stromal activation in actual melanomas." (PMID 28448494, 2017). "We noted that the lung cancer tumor bed contained a higher relative concentration of CCL3 and CCL4 compared with that of melanoma." (PMID 40553564, 2025). "MePip-SF5 upregulated Ccl3 in vitro; however, its pulmonary expression levels were downregulated in MePip-SF5-treated animals with melanoma metastasis." (PMID 37998354, 2023). "In a murine melanoma model, it has also been observed that TLR2-activated MCs can recruit NK cells through the secretion of high doses of CCL3." (PMID 37376140, 2023). "Immune suppressive effects of increased CCL3 have been observed in melanoma and higher levels of CCR5 ligands, CCL3, CCL4 and CCL5, correlated with accumulation of CCR5 + MDSCs in melanoma lesions and tumor progression." (PMID 37964379, 2023). "In the B16.F10 mouse melanoma model, the TLR2 agonist Pam3CSK4 induced MCs to release cytokines such as IL-6 and CCL3, which mediated a direct antiproliferative effect on tumor cells and the recruitment of NK and T cells, respectively." (PMID 37376140, 2023). "In a melanoma mouse model and patients with melanoma, the CCR5+ MDSCs accumulated in tumor tissues were positively correlated with the upregulation of CCL3, CCL4, and CCL5." (PMID 34527668, 2021). "In melanoma, B cells expressing CCL4, CCL3, and CCL5 attracted T cells to sustain a pro-inflammatory environment." (PMID 34503058, 2021). "An additional study reports a significant expression change of six chemokines (namely, CCL2, CCL3, CCL4, CCL5, CXCL9, and CXCL10) related to the lymphocyte infiltration in the melanoma tissue." (PMID 33302400, 2020). "Expression was confirmed to be significantly different in melanoma compared to the healthy controls, for IL-1Ra (recognized as ILRn by GEPIA2), IL-7, MIP-1a (recognized as CCL3 by GEPIA2), and MIP-1b (recognized as CCL4 by GEPIA2)." (PMID 33302400, 2020). "Basophil release of chemokines, such as CCL3 and CCL4, are also thought to play a role in attracting T cells into tumors, which in a melanoma mouse model, led to tumor rejection." (PMID 32645919, 2020).
melanoma (continued). "Further dissection of cluster 1 induced in IL-32–treated tumors showed significantly increased protein levels of the CCR5-binding chemokines CCL3, CCL4, CCL5, and CXCL2, corroborating the observations in IL-32hi human melanoma." (PMID 32841222, 2020). "For instance, expression of CCL3, CCL5 and CXCL2 in melanoma-treated DRG cells increased up to 3.5-, 4- and 3-fold, respectively, compared to control DRG cells (p<0.05, n = 3)." (PMID 27227315, 2016). "We have previously shown that reovirus infection of human melanoma cell lines induces a potentially immunogenic form of cell death with the release of RANTES (CCL5), IL-8, MIP-1α (CCL3) and MIP-1β (CCL4)." (PMID 21338484, 2011). "MIP-1α (Macrophage Inflammatory Protein 1-alpha), also known as CCL3, is a chemokine that attracts immune cells like T cells, macrophages, and dendritic cells to the tumor, influencing the immune response against melanoma." (PMID 41596411, 2026). "Based on these data, we next set out to determine what characteristics of lung cancer may contribute to the higher levels of CD8+ T cell–dependent CCL3 and CCL4 production compared with melanoma." (PMID 40553564, 2025). "Additionally, a rise in other cytokines, including IFN-α, IFN-γ, IL-10, CCL3, and CXCL10, was seen in both melanoma-treated groups receiving LIVP-RFP or LIVP-FlaB-RFP." (PMID 37112810, 2023). "Interestingly, a subset of SASP components, including cytokines CCL2, CCL3, CXCL12, cathepsin CTSD, or the protease inhibitor SERPINE1, are secreted in a RAB27A‐dependent manner in senescent melanoma cells." (PMID 36087066, 2022). "Interestingly, CCR5 is more highly expressed on tumor infiltrating monocytic MDSC than on peripheral cells and high concentrations of CCL3, CCL4, and CCL5 are found in melanoma lesions, potentially explaining the enrichment of CCR5+ MDSC in tumors." (PMID 30420855, 2018). "Moreover, it was recently found that CCR5 is expressed on MDSC in RET transgenic melanoma-bearing mice and melanoma patients, playing an important role in their recruitment to the tumor microenvironment via the CCR5 ligands (CCL3, CCL4, and CCL5)." (PMID 29942309, 2018). "CCL4 and CCL3 may mediate the recruitment of CD8+ T cells and regulatory T cells within melanoma lesions." (PMID 29157311, 2017). "Lipopolysaccharides can stimulate normal human melanocytes to produce IL-1β, TNFα, IL-6, IL-8, CCL2, CCl3, and CCL5, and chemotherapy of melanoma-bearing mice results in enhanced expression of CCL5 and the CXCR3 ligands CXCL9, CXCL10, and CXCl11 by tumor cells." (PMID 22745913, 2012). "In studies using neuroblastoma and melanoma murine models, the absence of CD200/CD200R signaling (using CD200R- mice) caused TAMCs to upregulate CCL24 and CCL8 levels but downregulate the production of CXCL3, CXCL2, and CCL3." (PMID 38137547, 2023). "Also in melanoma, increasing concentrations of CCR5 ligands were found in the tumor, such as CCL3/4/5, which could also lead to the infiltration of CCR5+ MDSCs." (PMID 34503058, 2021). "It was discerned that within Flu treated B16-F10 melanoma sites, there were no alteration in the levels of CCL2, CCL3, and CCL5, which are pivotal in mediating neutrophil recruitment." (PMID 40226609, 2025). "For example, in melanoma, the lack of CCR5 ligands (CCL3, CCL4, CCL5) and CXCR3 ligands (CXCL9 and CXCL10) has been associated with limited infiltration of antigen-specific T cells." (PMID 30873179, 2019). "Thus, the production of CCL24 and CCL8, and the reduction of CXCL3, CXCL2, and CCL3 in TAMCs, explain why mice lacking intact CD200/CD200R signaling more potently rejected neuroblastoma and melanoma tumors relative to wild-type conditions." (PMID 38137547, 2023).
colitis (50 papers, 2007 to 2025). Inflammation of the colon. "In mice, neutralization of MIP-1α ameliorated CDI colitis and deficiency of CCL3 reduced toxin A-mediated enteritis." (PMID 39923847, 2025). "CCL3/CCR5 accumulation of tumor-associated fibroblasts also have been reported to be important in colitis-related carcinogenesis and oral tumor formation." (PMID 32349303, 2020). "In C57BL/6J mice infected with C. difficile VPI10463, citrulline ameliorated colitis by reducing colonic Ccl3 mRNA expression." (PMID 39923847, 2025). "In the studies that follow, we review how CCL3/CCR5 signaling influences key stromal and immune cell populations to drive colitis-associated carcinogenesis, tumor–stroma interactions, and metastatic progression." (PMID 41153795, 2025). "Colons from p47phox−/− mice with DSS colitis were notable for significantly increased expression of granulocyte-colony stimulating factor (G-csf), chemokine (C-C motif) ligand 3 (Ccl3), and chemokine (C-X-C motif) ligand 2 (Cxcl2) compared to controls." (PMID 27044504, 2016). "We previously demonstrated that cancer-associated fibroblasts (CAFs) accumulate at tumor sites through the interaction between a chemokine, CCL3, and its receptor, CCR5, in the late phase of colitis-associated colon carcinogenesis." (PMID 27340784, 2016). "However, and in contrast, the DSS-induced colitis caused significantly increased levels of CXCL1, CCL2, CCL3, CCL11, G-CSF, and GM-CSF in Mcpt-4ΔCre mice as compared to Mcpt-4fl/fl mice." (PMID 40697820, 2025). "Similarly, less pronounced activation of the NF-κβ signaling pathway and decreased expression of inflammatory cytokines, including IL-1β, IL-6, MCP1, and CCL3 were observed in the colon of KO to WT compared to WT chimera mice with DSS colitis." (PMID 35743072, 2022). "After 7 days of induced colitis, upregulation of the expression of 22 genes (Ccl2, Ccl3, Ccl4, Ccl5, Ccl6, Ccl7, Ccl12, Ccl17, Cxcl1, Cxcl2, Cxcl6, Cxcl9, Cxcl11, Ccr1, Ccr2, Ccr3, Ccr5, Ccr8, Cxcr2, Csf3, Osm, and Spp1) was observed in the CβG− group compared to the HβG- control group." (PMID 35163326, 2022). "To evaluate colitis severity, we measured the expression of different pro-inflammatory cytokines and chemokines and found that the same supplement suppressed the pro-inflammatory cytokines IL-6 and TNFα and the chemokines Cxcl1 and Ccl3." (PMID 34071180, 2021). "Therefore, blocking the signal transmission in CCL2/CCR2 axis and CCL3/CCR1 axis might be an important method for L. acidophilus FAHWH11L56 to potentially relieve colitis." (PMID 36499169, 2022). "Accordingly, we observed that the expression levels of genes encoding chemokines (Ccl3, Ccl4, and Ccl6), chemokine receptors (Ccr1, Ccr5, Cxcr2, Cxcl1, Cxcl2, and Cxcl13), and inflammatory factors (Mpo, Il-1β, and Il12) were increased in mice with DSS-induced colitis." (PMID 34795650, 2021). "In our work, the defect of Mcpt-4 gene led to colitis mice producing higher levels of chemokines especially CXCL1, CCL2, CCL3, and CCL11." (PMID 40697820, 2025). "Transcription levels of Cxcl9, Ccl3, Ccl4, and Ccl5, which facilitate effector CD8+ T-cell extravasation into tissues, were significantly lower in the tumors of colitis mice than in that of normal mice." (PMID 37605139, 2023). "The expression of Il1a, Ccl5, Il1b, Ccl3, and Cxcl1 were significantly elevated in CD45+ cells from Il17b-/- colitis mice (P < 0.05)." (PMID 36814913, 2023). "In our model of colitis we found the expression of chemokines such as CCL2 and CCL3 and infiltration of neutrophils was decreased in b2KO mice." (PMID 36440681, 2023). "Importantly, we found that growth factors (GFs) like VEGF, IGF, and PDGF as well as chemo-cytokines CCL2, CCL3, CCL4, CCL5, and CCL20 were significantly upregulated in colitis’s colonic tissues." (PMID 37691056, 2023).